ISCA2 (iron-sulfur cluster assembly 2)
Description:
Involved in the maturation of mitochondrial 4Fe-4S proteins functioning late in the iron-sulfur cluster assembly pathway. May be involved in the binding of an intermediate of Fe/S cluster assembly.
Synonyms: HBLD1; ISA2; MMDS4; c14_5557
Tractability: PROTAC: its protein half-life has been measured.
Gene: Protein-coding gene on chromosome 14 (74,493,756 to 74,497,106, forward strand). Ensembl gene ENSG00000165898.
Subcellular location: Mitochondrion
Pathways (Reactome):
Metabolism: Maturation of TCA enzymes and regulation of TCA cycle; Mitochondrial iron-sulfur cluster biogenesis
Gene Ontology:
Molecular function: identical protein binding; protein binding; 2 iron, 2 sulfur cluster binding; 4 iron, 4 sulfur cluster binding; iron ion binding; iron-sulfur cluster binding
Biological process: protein maturation; iron-sulfur cluster assembly
Cellular component: iron-sulfur cluster assembly complex; mitochondrial [4Fe-4S] assembly complex; mitochondrion; mitochondrial matrix
Genetic constraint (gnomAD): Loss-of-function variants: 21 observed, 17.78 expected, observed/expected ratio (o/e) 1.18, 90% interval 0.84 to 1.68. The synonymous counts are far from expectation, so gnomAD's model fits this gene poorly and the ratio says little. Missense variants: 181 observed, 169.28 expected, observed/expected ratio (o/e) 1.07, 90% interval 0.95 to 1.21. Synonymous variants: 107 observed, 75.87 expected, observed/expected ratio (o/e) 1.41, 90% interval 1.21 to 1.66.
Gene-disease validity (ClinGen):
ClinGen rates the evidence that ISCA2 causes each of these diseases.
mitochondrial disease (autosomal recessive): Definitive.
Homologues: Orthologues: chimpanzee ISCA2 (99% identical), macaque ISCA2 (97% identical), dog ISCA2 (89% identical), rabbit ISCA2 (89% identical), guinea pig ISCA2 (88% identical), pig ISCA2 (86% identical), mouse Isca2 (84% identical), rat Isca2 (84% identical), rat Isca2-ps1 (82% identical), zebrafish isca2 (52% identical), Drosophila melanogaster CG13623 (44% identical), Caenorhabditis elegans Y54G11A.9 (39% identical). Paralogues in human: ISCA1 (23% identical).
Diseases named in the same sentence as ISCA2 in open-access papers:
ISCA2 is named in the same sentence as 20 diseases in open-access papers, as found by Europe PMC text mining. Sharing a sentence is not in itself a finding about the gene and the disease. The quoted sentences say what the papers report.
multiple mitochondrial dysfunctions syndromes (7 papers, 2018 to 2022). "ISCA2 is required for Iron-Sulfur cluster assembly and plays an essential role in the pathogenesis of multiple mitochondrial dysfunction syndromes." (PMID 36685880, 2022). "Defects in several proteins involved in the biosynthesis and trafficking of [4Fe-4S] clusters are associated with multiple mitochondrial dysfunctions syndromes (MMDS), with NFU1 causing MMDS1, BOLA3 causing MMDS2, IBA57 causing MMDS3, ISCA2 causing MMDS4, and ISCA1 causing MMDS5." (PMID 32151725, 2020). "The methodology we have adopted was based on Pubmed searches using “multiple mitochondrial dysfunction syndrome”, “NFU1”, “BOLA3”, “IBA57”, “ISCA2”, and “ISCA1” as keywords." (PMID 34440194, 2021). "Mutations in ISCA2 and IBA57 genes have been reported in patients affected by multiple mitochondrial dysfunctions syndromes (MMDS), specifically MMDS3 for IBA5722–28 and MMDS4 for ISCA229,30." (PMID 31831856, 2019). "Defects in ISCA1, ISCA2 and IBA57 have been associated with numerous mitochondrial diseases now categorized as multiple mitochondrial dysfunctions syndromes MMDS3 (IBA57), MMDS4 (ISCA2), and MMDS5 (ISCA1)." (PMID 30200358, 2018). "Defects in protein components of the mitochondrial ISC machinery are associated with numerous diseases, including Friedreich ataxia (defects in frataxin), myopathy (defects in ISCU or FDX2), and multiple mitochondrial dysfunction syndromes (defects in NFU1, BOLA3, ISCA2, and IBA57)." (PMID 30200358, 2018).
clear cell renal cell carcinoma (6 papers, 2022 to 2024). "The inhibition of ISCA2 can significantly reduce the xenograft growth of clear cell renal cell carcinoma." (PMID 36685880, 2022). "Moreover, ISCA2 inhibition in clear cell renal cell carcinoma has been shown to decrease HIF-1/2α levels and induce ferroptosis by disrupting iron metabolism." (PMID 39280009, 2024). "The inhibition of iron-sulfur cluster assembly 2 (ISCA2) at a late stage of mitochondrial ISC machinery can decrease HIF-1/2α levels and promote ferroptosis in clear cell renal cell carcinoma (ccRCC)." (PMID 37345031, 2023). "More importantly, the results of immunohistochemistry showed that the expression of NFU1, ISCA1, ISCA2 and C1ORF69 in normal tissues was higher than that in renal clear cell carcinoma tissues." (PMID 36385109, 2022). "The results of immunohistochemistry showed that the expression levels of NFU1, ISCA1, ISCA2 and C1ORF69 in normal tissues were higher than those in renal clear cell carcinoma tissues, which further verified our previous hypotheses." (PMID 36385109, 2022).
leukoencephalopathies (2 papers, 2018 to 2024). "It is also a quite common finding in Iron-sulfur cluster related leukoencephalopathies, particularly those caused by GLRX5, ISCA2, or IBA57 mutations." (PMID 29615062, 2018).
multiple mitochondrial dysfunctions syndrome 4 (2 papers, 2019 to 2024). Any fatal multiple mitochondrial dysfunctions syndrome in which the cause of the disease is a mutation in the ISCA2 gene. "Iron–sulfur cluster assembly 2 (ISCA2) deficiency is linked to an autosomal recessive disorder known as multiple mitochondrial dysfunctions syndrome 4 (MMDS4)." (PMID 39544370, 2024). "Multiple Mitochondrial Dysfunctions Syndrome 4 (MMDS4) is manifested as a result of ISCA2 mutations." (PMID 31279336, 2019).
epilepsy (1 paper, 2024). A brain disorder characterized by episodes of abnormally increased neuronal discharge resulting in transient episodes of sensory or motor neurological dysfunction, or psychic dysfunction. "Additional seizure- and epilepsy-associated proteins identified in PTE+ and PTE− cortex and hippocampus include Scnb1, Isca2, Wdr4, and Dkc1." (PMID 38474127, 2024).
kidney cancer (1 paper, 2022). Primary or metastatic malignant neoplasm involving the kidney. "In our research, we found that NFU1, ISCA1, ISCA2, C1ORF69, and BLOA3 were altered significantly in kidney cancer tissues in multiple datasets." (PMID 36385109, 2022).
leukodystrophy (1 paper, 2018). Leukodystrophies are a group of rare, progressive, metabolic, genetic diseases that affect the brain, spinal cord and often the peripheral nerves. "Radiological findings showed a combination of features, most notably, leukodystrophy of the brainstem with longitudinally extensive spinal cord involvement and elevated lactate, and illustrate the pleiotropic effects of abnormal ISCA2 gene function." (PMID 29297947, 2018).
Nephropathy (1 paper, 2024). A nonspecific term referring to disease or damage of the kidneys. "Additionally, at the RNA level, elevated expression of ISCA2 potentially increased the risk of nephropathy and peripheral circulatory complications in T2DM patients." (PMID 39280009, 2024).
Nystagmus (1 paper, 2020). Rhythmic, involuntary oscillations of one or both eyes related to abnormality in fixation, conjugate gaze, or vestibular mechanisms. "A comprehensive literature review indicates hypotonia, motor regression, feeding difficulty, and nystagmus in LBSL patients caused by ISCA2 mutations." (PMID 33182419, 2020).
cancer (4 papers, 2022 to 2023). A tumor composed of atypical neoplastic, often pleomorphic cells that invade other tissues. "Therefore, targeting ISCA2 may be a promising therapeutic approach to inhibit HIF-1/2α and promote ferroptosis in von Hippel–Lindau-deficient cancer cells." (PMID 37345031, 2023). "Other ISC assembly pharmaceutical inhibitors, eprenetapopt or compound #25, reduce ISC biogenesis, restrict cancer cell proliferation, and trigger ferroptosis by inhibiting NFS1 or ISCA2." (PMID 37345031, 2023). "There were significant differences in the mRNA expression levels of ISCA1, ISCA2, C1ORF69 and NFU1 in KIRC among different tumor grades and individual cancer stages." (PMID 36385109, 2022). "Moreover, there were significant differences in the mRNA expression levels of ISCA1, ISCA2, C1ORF69 and NFU1 in KIRC among different tumor grades and individual cancer stages." (PMID 36385109, 2022). "In addation, CAT, POLE, NTHL1, ATP7B, ISCA2, NDUFA1 and NDUFB2 have also been reported to play a key role in the development of cancers." (PMID 36685880, 2022). "The results showed that the expression levels of ISCA1, ISCA2, C1ORF69 and NFU1 were significantly different in normal tissues versus KIRC tumor tissues (p < 0.01), among different tumor grades (p < 0.01), and among different individual cancer stages (p < 0.01)." (PMID 36385109, 2022).
tumor (4 papers, 2022). "ISCA2 levels are decreased with pVHL loss and patients with low ISCA2 levels have significantly decreased overall survival suggesting that ISCA2 may play a tumor suppressor role." (PMID 36097192, 2022). "Pathologist (DS) scoring of cores from uninvolved and tumor tissue from 19 patients with ccRCC showed a significance decrease in H-Score between ccRCC tissue compared to uninvolved kidney confirming that ISCA2 levels are significantly lower in ccRCC than in normal kidney." (PMID 36097192, 2022). "We evaluated the expression differences of ISCA1, ISCA2, C1ORF69 and NFU1 normal tissues versus tumor tissues and among tumor tissues of KIRC." (PMID 36385109, 2022). "In addition, we also analyzed the expression of NFU1, ISCA1, ISCA2, C1ORF69 and BLOA3 genes in various tumor types through the oncomine database." (PMID 36385109, 2022).
mitochondrial disease (2 papers, 2018 to 2021). "Iron supplementation significantly elevated the expression of Cox10, the mutations of which are associated with mitochondrial disease, and Bola3 and Isca2, the mutations of which are associated with MMDS and/or oxidative phosphorylation activity." (PMID 34031430, 2021).
ISCA2 also shares sentences with these, for which no sentence is quoted: Encephalopathy (1 paper); Failure to thrive (1); genetic disorders (1); metabolic myopathies (1); myopathy (1); Onset (1); optic atrophy (1); renal carcinoma (1).